ALOX5 (arachidonate 5-lipoxygenase)
Description:
Catalyzes the oxygenation of arachidonate ((5Z,8Z,11Z,14Z)- eicosatetraenoate) to 5-hydroperoxyeicosatetraenoate (5-HPETE) followed by the dehydration to 5,6-epoxyeicosatetraenoate (Leukotriene A4/LTA4), the first two steps in the biosynthesis of leukotrienes, which are potent mediators of inflammation. Also catalyzes the oxygenation of arachidonate into 8-hydroperoxyicosatetraenoate (8-HPETE) and 12-hydroperoxyicosatetraenoate (12-HPETE). Displays lipoxin synthase activity being able to convert (15S)-HETE into a conjugate tetraene. Although arachidonate is the preferred substrate, this enzyme can also metabolize oxidized fatty acids derived from arachidonate such as (15S)-HETE, eicosapentaenoate (EPA) such as (18R)- and (18S)-HEPE or docosahexaenoate (DHA) which lead to the formation of specialized pro-resolving mediators (SPM) lipoxin and resolvins E and D respectively, therefore it participates in anti-inflammatory responses. Oxidation of DHA directly inhibits endothelial cell proliferation and sprouting angiogenesis via peroxisome proliferator-activated receptor gamma (PPARgamma) (By similarity). It does not catalyze the oxygenation of linoleic acid and does not convert (5S)-HETE to lipoxin isomers. In addition to inflammatory processes, it participates in dendritic cell migration, wound healing through an antioxidant mechanism based on heme oxygenase-1 (HO-1) regulation expression, monocyte adhesion to the endothelium via ITGAM expression on monocytes (By similarity). Moreover, it helps establish an adaptive humoral immunity by regulating primary resting B cells and follicular helper T cells and participates in the CD40-induced production of reactive oxygen species (ROS) after CD40 ligation in B cells through interaction with PIK3R1 that bridges ALOX5 with CD40. May also play a role in glucose homeostasis, regulation of insulin secretion and palmitic acid-induced insulin resistance via AMPK (By similarity). Can regulate bone mineralization and fat cell differentiation increases in induced pluripotent stem cells (By similarity).
Synonyms: 5-LO; LOG5; 5-LOX; 5LPG
Tractability: Small molecule: an approved drug acts on it; a structure with a bound ligand is known; a high-quality ligand is known; it belongs to a druggable protein family. Antibody: UniProt places it where antibodies can reach, with high confidence; its Gene Ontology location is reachable by antibodies, with high confidence. PROTAC: its protein half-life has been measured; a small molecule that binds it is known.
Target class: Enzyme; Oxidoreductase
Chemical probes: CURCUMIN PYRAZOLE, NYMPHAEOL A, PD082027, PD134522
Gene: Protein-coding gene on chromosome 10 (45,374,150 to 45,446,121, forward strand). Ensembl gene ENSG00000012779.
Subcellular location: Cytoplasm; Nucleus matrix; Nucleus membrane; Cytoplasm, perinuclear region; Cytoplasm, cytosol; Nucleus envelope; Nucleus intermembrane space
Subcellular location (Human Protein Atlas): Nucleoplasm
Pathways (Reactome):
Metabolism: Biosynthesis of D-series resolvins; Biosynthesis of DPAn-3-derived 13-series resolvins; Biosynthesis of DPAn-3-derived maresins; Biosynthesis of DPAn-3-derived protectins and resolvins; Biosynthesis of E-series 18(R)-resolvins; Biosynthesis of E-series 18(S)-resolvins; Biosynthesis of Lipoxins (LX); Biosynthesis of aspirin-triggered D-series resolvins; Biosynthesis of electrophilic ω-3 PUFA oxo-derivatives; Biosynthesis of maresins; Synthesis of 5-eicosatetraenoic acids; Synthesis of Leukotrienes (LT) and Eoxins (EX)
Immune System: Interleukin-18 signaling; Interleukin-4 and Interleukin-13 signaling; Neutrophil degranulation
Gene Ontology:
Molecular function: arachidonate 12(S)-lipoxygenase activity; arachidonate 5-lipoxygenase activity; arachidonate 8(S)-lipoxygenase activity; iron ion binding; protein binding; oxidoreductase activity; oxidoreductase activity, acting on single donors with incorporation of molecular oxygen; metal ion binding; oxidoreductase activity, acting on single donors with incorporation of molecular oxygen, incorporation of two atoms of oxygen
Biological process: leukocyte chemotaxis involved in inflammatory response; leukotriene A4 biosynthetic process; leukotriene biosynthetic process; lipoxin biosynthetic process; negative regulation of inflammatory response; regulation of inflammatory response; regulation of reactive oxygen species biosynthetic process; arachidonate metabolic process; dendritic cell migration; glucose homeostasis; humoral immune response; leukocyte migration involved in inflammatory response; leukotriene metabolic process; lipoxygenase pathway; long-chain fatty acid biosynthetic process; negative regulation of angiogenesis; negative regulation of endothelial cell proliferation; negative regulation of response to endoplasmic reticulum stress; negative regulation of sprouting angiogenesis; negative regulation of vascular wound healing; negative regulation of wound healing; positive regulation of bone mineralization; positive regulation of leukocyte adhesion to arterial endothelial cell; regulation of cellular response to oxidative stress; regulation of cytokine production involved in inflammatory response; and 7 more
Cellular component: cytoplasm; cytosol; extracellular region; nuclear envelope; nuclear envelope lumen; nuclear matrix; nuclear membrane; nucleoplasm; perinuclear region of cytoplasm; ficolin-1-rich granule lumen; secretory granule lumen; nucleus
Genetic constraint (gnomAD): Loss-of-function variants: 64 observed, 84.44 expected, observed/expected ratio (o/e) 0.76, 90% interval 0.62 to 0.93. The upper end of that interval is the gene's LOEUF score, 0.93, which puts it in group 3 of 6, group 1 being the genes least tolerant of losing a copy. Missense variants: 822 observed, 892.86 expected, observed/expected ratio (o/e) 0.92, 90% interval 0.87 to 0.98. Synonymous variants: 388 observed, 355.52 expected, observed/expected ratio (o/e) 1.09, 90% interval 1 to 1.19.
Homologues: Orthologues: chimpanzee ALOX5 (99% identical), macaque ALOX5 (98% identical), rabbit ALOX5 (94% identical), dog ALOX5 (94% identical), rat Alox5 (94% identical), mouse Alox5 (93% identical), pig ALOX5 (93% identical), guinea pig ALOX5 (91% identical), tropical clawed frog alox5 (78% identical), zebrafish alox5a (74% identical), zebrafish alox5b.3 (59% identical), zebrafish alox5b.2 (57% identical), and 1 more. Paralogues in human: ALOX15B (42% identical), ALOXE3 (41% identical), ALOX12 (41% identical), ALOX12B (41% identical), ALOX15 (39% identical).
Diseases named in the same sentence as ALOX5 in open-access papers:
ALOX5 is named in the same sentence as 279 diseases in open-access papers, as found by Europe PMC text mining. Sharing a sentence is not in itself a finding about the gene and the disease. The quoted sentences say what the papers report.
asthma (76 papers, 2004 to 2026). "Previous research has indicated that polymorphisms in the ALOX5 promoter can influence the response to asthma treatment." (PMID 41030501, 2025). "Several mutations occur within the ALOX5 promoter region and are associated with airway hyperresponsiveness and asthma severity." (PMID 37109111, 2023). "CTD associations of ALOX5 include asthma, atherosclerosis, insulin resistance, Alzheimer’s disease (AD), neurodegenerative diseases, dyslipidemias." (PMID 33546175, 2021). "Arachidonate can be converted by 5-lipoxygenase encoded by ALOX5 to leukotriene, which is released during an asthma attack and is responsible for the bronchoconstriction." (PMID 33156843, 2020). "HTR2C, CYP1B1, CYP19A1, ESR1, ESR2, PDR, and AR are found to be interrelated to hormonal disorders; ABCC1, NQO1, TIMP1, ADRB2, and ALOX5 are associated with asthma." (PMID 29861771, 2018). "Studies of adults with asthma suggest that heterogeneity in response to montelukast is partly determined by a polymorphism in the arachidonate 5-lipoxygenase (ALOX5) gene promoter." (PMID 25212745, 2014). "As shown in, 6 essential oil compositions could act on PLA2G4A and ALOX5 and be associated with asthma." (PMID 35702766, 2023). "However, in the sensitivity analysis, Greenlander with homozygous AA genotype of ALOX5 SNP rs892690 had a significantly increased risk of ever asthma compared to GG genotype (P < 0.05)." (PMID 28740106, 2017). "More recently, ALOX5 polymorphisms have been associated with increased cysteinyl leukotriene production as well as reduced lung function in children with poorly controlled asthma." (PMID 27990118, 2016). "The ALOX5 variants that confer susceptibility to asthma, therefore, may be of pharmacogenetic significance if an inadequate quantity of ALOX5 protein is available as a drug target." (PMID 27990118, 2016). "Thus, the leukotriene pathway, and in particular the ALOX5 gene, are implicated in both asthma and sickle cell disease severity and morbidity." (PMID 21490765, 2011). "It is possible that in MS, as found in asthma, these promoter variations may affect disease modification rather than disease susceptibility – an idea worthy of further investigation if ALOX5 inhibitors were considered for MS treatment." (PMID 18366677, 2008). "ALOX5 promoter variants may, therefore, be a risk factor for worse asthma outcomes." (PMID 27990118, 2016). "Early studies identified addition and deletion variants (wildtype n = 5; variant n ≠ 5) in the core promoter of the ALOX5 gene that were associated with diminished promoter-reporter activity in tissue culture which has been confirmed in both healthy African Americans and patients with asthma." (PMID 21490765, 2011). "To determine the requirement of cysLTs for the asthma phenotype, we also infected Alox5-/- and montelukast-treated mice." (PMID 41573550, 2025). "Analysis of the biomarker-disease network map revealed that ALOX5, HMOX1, and PLA2G7 were strongly associated with asthma." (PMID 41030501, 2025). "The second most prominent asthma-related PGAP3-upregulated gene in ASM found in our data set is ALOX5 (FC = 4.88)." (PMID 40131902, 2025). "ALOX5 has previously been shown to contribute to asthma in ASM through leukotrienes derived from arachidonic acid metabolism." (PMID 40131902, 2025). "RNA-seq studies of ASM transfected with PGAP3 demonstrated significantly increased levels of genes linked to asthma including GATA3 and ALOX5." (PMID 40131902, 2025). "In fact, depending on the copy numbers of the Sp1-bing motif in the ALOX5 gene promoter (that can be 5/5, 5/x or x/x, where x differs from 5), the response to montelukast in adults with asthma is known to be different." (PMID 36013002, 2022). "ALOX5 (tandem repeats of the Sp1-binding domain) is likely to influence asthma exacerbations in patients taking LTMs." (PMID 35887565, 2022).
asthma (continued). "Antagonists for leukotriene receptor and Arachidonate 5 lipoxygenase (ALOX5) have been developed for the treatment of seasonal allergies and asthma." (PMID 35744996, 2022). "More importantly, 11 mRNAs were overlapped in our sequencing data, MalaCards database and asthma-associated genes, including IL4, IL-10, MMP9, VCAM-1, Il1rl1, Alox5, Il1rn, Ccr3, Cysltr1, Epx, and Ccl24." (PMID 31231429, 2019). "We have previously investigated the role of polymorphic variation in the genes of the 5-lipoxygenase pathway e.g. ALOX5, LTC4S, CYSLTR1 in asthma and allergy susceptibility and as determinants of clinical responses to therapies targeting this pathway." (PMID 22206291, 2011). "ALOX5, HMOX1, and PLA2G7 are genes that have been implicated in asthma." (PMID 41030501, 2025). "Fevipiprant, which targets PTGDR2, has been evaluated in clinical trials for asthma and atopic dermatitis; Zileuton, a 5-lipoxygenase inhibitor that reduces leukotriene synthesis, targets ALOX5; and captopril, an angiotensin-converting enzyme inhibitor, targets ACE." (PMID 41395465, 2025). "Alox5-/- and montelukast-treated mice also showed reduced mucous metaplasia, type 2 cytokine expression and airways responsiveness, suggesting that lung cysLTs are required for development of the asthma phenotype after RV infection." (PMID 41573550, 2025). "Moreover, RNA-seq studies demonstrated that increased PGAP3 expression in ASM increased levels of genes previously linked to asthma including GATA3 and ALOX5." (PMID 40131902, 2025). "In addition, when ASM from non-asthmatics are transfected with PGAP3, the increased levels of PGAP3 increase ASM proliferation and contractility, and increase levels of genes previously linked to asthma including GATA3 and ALOX5." (PMID 40131902, 2025). "In addition, when ASM from non-asthmatics are transfected with PGAP3, the increased levels of PGAP3 increased ASM proliferation and contractility, and increased levels of genes previously linked to asthma including GATA3 and ALOX5." (PMID 40131902, 2025). "In children with asthma, the genotype of the ALOX5 promoter may be related to response to treatment with leukotriene receptor antagonists." (PMID 39247132, 2024). "Genetic variations in the promoter region of ALOX5 may induce a reduced drug response to montelukast sodium in patients with asthma, leading to pharmacogene." (PMID 35866375, 2022). "In addition, both ALOX5 and IL5RA have been identified as susceptibility genes associated with asthma and asthmatic inflammation in humans, and a monoclonal antibody to the IL5RA ligand, IL5, is FDA-approved for the treatment of severe eosinophilic asthma." (PMID 35169481, 2021). "Zileuton is an inhibitor of ALOX5 and is used to prevent asthma attacks in adults and children." (PMID 31440260, 2019). "Variable number tandem repeat sequences located in the Sp1-binding motif within the promotor region of the ALOX5 gene are associated with leukotriene burden and bronchoconstriction independent of asthma risk." (PMID 27990118, 2016). "Polymorphisms that alter response to asthma therapy include Arg16Gly, Gln27Glu, Thr164Ile for β-agonist receptor, polymorphism of glucocorticoid receptor gene, CRHR1 variants and polymorphism of LTC4S, ALOX5." (PMID 21206697, 2010). "At present, reports on the effect of the ALOX5 gene on myoblasts are lacking; however, the ALOX5 gene has been reported to be associated with the pathogenesis of many diseases, such as asthma, allergic rhinitis and other allergic diseases, cardiovascular diseases, multiple sclerosis, and tumors." (PMID 37372393, 2023). "Although the pathways that mediate PGAP3 induced ASM proliferation and contractility are not known, RNA-Sequencing of ASM expressing PGAP3 identified four genes significantly upregulated by PGAP3 that have known relevance with asthma (i.e., GATA3, ALOX5, BMP4, and SERPINB5)." (PMID 40131902, 2025).
asthma (continued). "Our subsequent molecular docking showed that each bioactive compounds (quercetin, wogonin, luteolin, naringenin, and kaempferol) of MGMD has favorable binding abilities with STAT3, PTGS2, JUN, VEGFA, EGFR, and ALOX5, further arguing the potential molecular mechanism of action of MGMD in asthma." (PMID 33968984, 2021). "The effects of ALOX5 rs892690 on ever asthma, LT-α rs2844484 and TNF-α rs1800629 on bronchitis were not considered significant with the adjusted thresholds, while the others remained significant after the correction." (PMID 28740106, 2017). "Consistently, the expression of SLC7A11, SLC3A2, and GPX-4 was also inhibited, while the level of ALOX5 was enhanced in lung tissues of asthma mice or IL-13-stimulated BEAS-2B cells, further demonstrating the initiation of ferroptosis during the development of asthma." (PMID 35154576, 2022).
atherosclerosis (52 papers, 2006 to 2026). A disease characterized by the build-up of fatty material and calcium deposition in the arterial wall resulting in partial or complete occlusion of the arterial lumen. "It reveals the association of ELOVL5 and ALOX5 with macrophage phenotypes, demonstrating their potential in regulating atherosclerosis-related inflammation." (PMID 41959723, 2026). "Reduced ALOX5 expression is partly responsible for resistance to atherosclerosis and variant ALOX5 genotypes identify a subpopulation with increased atherosclerosis." (PMID 39758846, 2024). "Genetic deficiency of ALOX5 in mice results in reduced development of atherosclerosis, despite increased lipid levels, fat mass, elevated glucose levels, and low fasting insulin levels." (PMID 36011386, 2022). "Genetic Associations Database (GAD) associates ALOX5 with blood pressure, T2D, atherosclerosis, and AD." (PMID 33546175, 2021). "Polymorphisms in genes involved in the leukotriene pathway have been linked to atherosclerosis in humans and Alox5 itself is a key molecule for atherosclerosis susceptibility in mice." (PMID 29208753, 2018). "Increased transcript levels of markers associated with atherosclerosis or cardiovascular impairments (Edn1, Selp, Alox5, and Icam1) further indicate plausible detrimental effects of CNP exposure on aortic tissue at 24 h post inhalation." (PMID 28637465, 2017). "In the present study of 6153 apparently healthy MESA participants at baseline, associations among ALOX5 SNPs and subclinical atherosclerosis as well as CHD events were examined." (PMID 27025886, 2016). "To date, a number of well‐powered case‐control studies have examined associations of ALOX5 gene variants with metrics of atherosclerosis and CHD, yet findings have so far been inconclusive." (PMID 27025886, 2016). "Despite these differences in design and genetic evaluation, both studies observed that polymorphisms in ALOX5 were associated with variation in measures of atherosclerosis (IMT in both studies; CorCP and AorCP in DHS)." (PMID 20592751, 2010). "ALOX5 has been identified as a gene that contributes to susceptibility to atherosclerosis in mice." (PMID 36011386, 2022). "Overall, whether ALOX5 variants associate with atherosclerosis or CHD is unclear, and potential interactions with PUFAs and race/ethnicity have not been collectively studied in a large cohort population." (PMID 27025886, 2016). "The present analysis examines common ALOX5 gene SNPs and their cross‐sectional association with subclinical atherosclerosis determined by common and internal cIMT values in 6153 participants of the Multi‐Ethnic Study of Atherosclerosis (MESA)." (PMID 27025886, 2016). "The arachidonate 5‐lipoxygenase enzyme plays a crucial role in mediating inflammation to maintain homeostasis, yet certain allelic variants of the 5‐lipoxygenase gene, ALOX5, may increase risk of atherosclerosis and coronary heart disease (CHD)." (PMID 27025886, 2016). "Through target identification and protein-protein interaction analyses, we identified ALOX5 as a pivotal hub gene-an enzyme critically involved in the pathogenesis of atherosclerosis." (PMID 41493682, 2026). "Based on GSEA results, ALOX5 was relevant to B Cell receptor signaling pathway, Chemokine signaling pathway, Lipid and atherosclerosis, Natural killer cell mediated cytotoxicity, NF−kappa B signaling pathway and NOD−like receptor signaling pathway." (PMID 40290492, 2025). "Another study reported the supposed modifying effect of a diet rich in omega-3 and -6 fatty acids on the relationship between ALOX5 tandem variability and atherosclerosis." (PMID 36009459, 2022). "ALOX12, ALOX5, and ALOX5AP polymorphisms are genetically associated with subclinical atherosclerosis and with disease biomarkers in families with type 2 diabetes." (PMID 36011386, 2022).